RN7SKP227 (RN7SK pseudogene 227)
Gene: Miscellaneous RNA gene on chromosome 3 (36,685,040 to 36,685,369, forward strand). Ensembl gene ENSG00000201315.
Homologues: Orthologues: chimpanzee 7SK (97% identical). Paralogues in human: 7SK (88% identical), RN7SKP48 (83% identical), RN7SKP118 (81% identical), RN7SKP185 (81% identical), RN7SKP187 (81% identical), RN7SKP174 (80% identical), RN7SKP178 (80% identical), RN7SKP62 (78% identical), RN7SKP55 (76% identical), RN7SKP76 (75% identical), RN7SKP160 (75% identical), RN7SKP292 (74% identical), and 284 more.